KCNJ3 (potassium inwardly rectifying channel subfamily J member 3)
Diseases named in the same sentence as KCNJ3 in open-access papers:
KCNJ3 is named in the same sentence as 48 diseases in open-access papers, as found by Europe PMC text mining. Sharing a sentence is not in itself a finding about the gene and the disease. The quoted sentences say what the papers report.
breast carcinoma (14 papers, 2004 to 2023). "Amongst the wide range of tumors of different origin listed in the GDC Data Portal, tumors from the uterus, skin and lung revealed the highest frequency of somatic mutations in KCNJ3, while breast cancer was least affected." (PMID 36483038, 2022). "CPSP risk 6 months after breast cancer surgery has previously been reported for haplotype A2 rs3111020-rs11895478 G-A of KCNJ3 and rs2835925 of KCNJ6." (PMID 33868360, 2021). "Amongst these, the potassium channel gene KCNJ3 (encoding for GIRK1 proteins) has been reported to be upregulated in tumors of patients with breast cancer and to correlate with positive lymph node status." (PMID 27835900, 2016). "Several studies suggested evidence for a role of GIRK1, the G-protein coupled inward rectifier K+ channel encoded by KCNJ3, in breast cancer." (PMID 27835900, 2016). "Malignant breast cancer cell lines express mRNAs encoding GIRK1 (but also GIRK2 and GIRK4) subunits and several splice variants of the KCNJ3 gene transcript." (PMID 27519272, 2016). "Next, we studied KCNJ3 mRNA expression levels of the TCGA data set to detect possible associations with clinically relevant breast cancer subsets." (PMID 27835900, 2016). "In conclusion, our data suggest that patients with ER positive breast cancer might be stratified into high risk and low risk groups based on the KCNJ3 levels in the tumor." (PMID 27835900, 2016). "KCNJ3, a gene encoding G-protein activated inwardly rectifying K (+) channel (GIRK1), is related to lymph node metastasis and prognosis in breast cancer patients." (PMID 36686667, 2022). "The current study provides insight into the cellular and molecular consequences of KCNJ3 overexpression in breast cancer cells and the mechanism upon clinical outcome in patients suffering from breast cancer." (PMID 27519272, 2016). "In order to gain additional insight into the cellular mechanisms that would lead to worse patient outcomes due to high levels of KCNJ3 in tumor cells, we performed a mammosphere formation assay with the ER positive breast cancer cell line MCF-7." (PMID 27835900, 2016). "This is further corroborated by multivariate Cox proportional hazard analysis, showing that KCNJ3 is an independent prognostic marker for ER positive breast cancer, being also independent from the PAM50 subtype of the patient." (PMID 27835900, 2016). "The ISH method presents a sensitive and specific detection technique that is an indispensable tool to efficiently investigate larger patient cohorts in order to derive possible prognostic and predictive information of KCNJ3 in breast cancer." (PMID 27698251, 2016). "Besides, the potassium channel gene KCNJ3 has been upregulated in non-small cell lung cancer, pancreatic cancer, and breast cancer." (PMID 36686667, 2022). "This is the first study to provide insight into the cellular and molecular consequences of KCNJ3 overexpression in breast cancer cells and the mechanism how overexpression could translate into the worsened clinical outcome in breast cancer." (PMID 27519272, 2016). "In order to validate KCNJ3 expression levels in tumor and normal cells, RNA in situ hybridization (ISH) was performed on breast cancer tissue samples to locate KCNJ3 expression in cancerous as well as in surrounding tumor stroma and normal breast epithelial cells." (PMID 27835900, 2016). "To validate our findings and to extend our analysis beyond the TCGA data set, we performed KCNJ3 RNA in situ hybridization (ISH) on 66 breast cancer patient samples that were available with clinical data and follow-up times from the estrogen receptor positive cohort GSE17705." (PMID 27835900, 2016). "Here we report two methods for the detection of KCNJ3 in archived FFPE human breast cancer tissue." (PMID 27698251, 2016).
breast carcinoma (continued). "In line with this, our data clearly demonstrate that KCNJ3 expression is associated with ER positive breast cancer and that KCNJ3 levels correlate with ESR1 mRNA expression levels but not with expression levels of other estrogen receptors." (PMID 27835900, 2016). "We aimed to study KCNJ3 levels in different breast cancer subtypes using gene expression data from the TCGA, to validate our findings using RNA in situ hybridization in a validation cohort (GEO ID GSE17705), and to study the prognostic value of KCNJ3 using survival analysis." (PMID 27835900, 2016). "This corroborates the correlation between KCNJ3 expression and breast cancer progression." (PMID 27519272, 2016). "In summary, Ab#1 yielded satisfactory results regarding specificity and sensitivity, and the protocol was further optimised for archived human FFPE breast cancer samples using patient sample #2 with high KCNJ3 mRNA expression levels (according to microarray data) as biological positive control." (PMID 27698251, 2016). "Thus, it remains to be determined whether and how GIRK1 and ER act together in same signaling pathways and further studies are needed to elucidate the mechanism of action of KCNJ3 upregulation in breast cancer." (PMID 27835900, 2016). "Overexpression the KCNJ3, a gene that encodes subunit 1 of G-protein activated inwardly rectifying K+ channel (GIRK1) in the primary tumor has been found to be associated with reduced survival times and increased lymph node metastasis in breast cancer patients." (PMID 27519272, 2016). "In order to pursue this goal, we aimed to establish methods for the detection of KCNJ3 gene products in formalin-fixed, paraffin-embedded (FFPE) breast cancer samples." (PMID 27698251, 2016). "We have analyzed > 1000 breast cancer patient samples of two independent data sets (TCGA: n = 905, GSE17705: n = 298) regarding their KCNJ3 expression in order to evaluate a potential prognostic role of this ion channel gene for breast cancer." (PMID 27835900, 2016). "To date, the mechanisms leading to KCNJ3 upregulation in breast carcinomas are not understood." (PMID 27835900, 2016). "However, no further details or survival data regarding KCNJ3 expression were given or discussed, as this study aimed to develop an ion channel gene signature (termed IC30) as prognostic tool in breast cancer, and KCNJ3 is not comprised in this final gene panel." (PMID 27835900, 2016). "Wild-type breast cancer MCF-7 cells were negative, in contrast to strong positivity of MCF-7 cells overexpressing KCNJ3." (PMID 27698251, 2016).
lymph node metastasis (6 papers, 2004 to 2022). "We observed increased KCNJ3 expression in tumors of patients who presented with positive lymph nodes when compared to those without lymph node metastasis at diagnosis (median 6.9 vs. 25.3 normalized counts; p < 0.001)." (PMID 27835900, 2016).
invasive breast carcinoma (5 papers, 2008 to 2016). A carcinoma that infiltrates the breast parenchyma. "Based on these results, we intended to study and validate KCNJ3 expression in invasive breast carcinoma samples as potential new prognostic biomarker." (PMID 27835900, 2016). "Stringer et al2 observed increased levels of KCNJ3 mRNA in primary invasive breast carcinomas when compared with corresponding normal breast tissue and found KCNJ3 mRNA levels positively correlating with the amount of metastatic lymph nodes." (PMID 27698251, 2016). "Taken this evidence together, it seems worthwhile to study KCNJ3 expression in invasive breast carcinoma to validate it as a new prognostic biomarker for this disease." (PMID 27698251, 2016).
non-small cell lung carcinoma (5 papers, 2004 to 2023). A group of at least three distinct histological types of lung cancer, including non-small cell squamous cell carcinoma, adenocarcinoma, and large cell carcinoma. "Upregulation of KCNJ3 gene products (i.e. GIRK1 mRNA and protein; synonyms: KGA, Kir3.1) was reported for non-small cell lung cancer and pancreatic adenocarcinomas." (PMID 27835900, 2016).
schizophrenia (5 papers, 2012 to 2019). A major psychotic disorder characterized by abnormalities in the perception or expression of reality. "A growing body of evidence implicates several calcium and potassium channels in the susceptibility of schizophrenia, such as CACNA1C (Cav1.2 α subunit), KCNN3 (SK3), KCNH3 (Ether-A-Go-Go), and KCNJ3 (Kir3.1)." (PMID 31920555, 2019). "A potassium ATP dependent channel (KCNJ3, potassium voltage-gated channel subfamily J member 3), which expression is inhibited in bipolar depression and schizophrenia, was down regulated in the Drosophila KD and the gene appeared as part of one of the significant pathways in the human GWAS." (PMID 28676676, 2017). "The analysis of transcript levels in the dorsolateral prefrontal cortex of postmortem brains from patients with schizophrenia and BPD and from healthy controls, revealed significantly lower KCNJ3 expression in patients compared with controls." (PMID 23675382, 2013).
Arrhythmia (3 papers, 2020 to 2025). Any cardiac rhythm other than the normal sinus rhythm. "Genetic variation in KCNJ3 is associated with arrhythmias, and blocking the channel in zebrafish improved the arrhythmogenic phenotype." (PMID 40791945, 2025).
atrial fibrillation (3 papers, 2015 to 2022). A disorder characterized by an electrocardiographic finding of a supraventricular arrhythmia characterized by the replacement of consistent P waves by rapid oscillations or fibrillatory waves that vary in size, shape and timing and are accompanied by an irregular ventricular response. "MiR-328 was reported to target CACNA1C/Cav1.2 and miR-30d could target KCNJ3/Kir3.1, which could lead to adverse electrical remodeling in atrial fibrillation." (PMID 33421993, 2021).
breast tumors (2 papers, 2016 to 2019). "To explore gene amplification as a possible cause for the observed increase in KCNJ3 mRNA expression levels in breast tumors, we studied the gene copy numbers of 890 TCGA patient samples." (PMID 27835900, 2016). "First, we investigated whether KCNJ3 mRNA expression is higher in breast tumors when compared to corresponding normal tissue." (PMID 27835900, 2016).
osteosarcoma (2 papers, 2019 to 2022). A usually aggressive malignant bone-forming mesenchymal neoplasm, predominantly affecting adolescents and young adults. "Results showed higher expression levels of RASGRP2 and KCNJ3 in two osteosarcoma cell groups (U20S and 143B) compared to the osteoblast cell group (hFOB)." (PMID 36686667, 2022). "The expression levels of RASGRP2 and KCNJ3 were upregulated in osteosarcoma cells, while the expression of ACTG2 was decreased." (PMID 36686667, 2022). "Western blotting was used to determine the level of KCNJ3 in U20S and 143B osteosarcoma cells with various doses of sunitinib." (PMID 36686667, 2022). "KCNJ3 expression was reduced in osteosarcoma cells (U20S and 143B) in a dose-dependent manner of sunitinib." (PMID 36686667, 2022). "We believed sunitinib might provide better treatment for osteosarcoma with elevated KCNJ3 expression." (PMID 36686667, 2022). "Sunitinib can promote osteosarcoma cell apoptosis with down-regulation of KCNJ3 expression." (PMID 36686667, 2022). "KCNJ3 may be a valuable prognostic marker for osteosarcoma development." (PMID 36686667, 2022).
Airway obstruction (1 paper, 2021). Obstruction of conducting airways of the lung. "Of them, KCNJ3 was identified to associated with lung function and airway obstruction in previous studies, though there is no data on emphysema." (PMID 34404834, 2021).
autism (1 paper, 2023). Persistent deficits in social interaction and communication and interaction as well as a markedly restricted repertoire of activity and interest as well as repetitive patterns of behavior. "(S) Log-normalized counts of transcripts for the autism-related transcription factor Auts2 and several neurotransmitter receptor and ion channel genes whose expression changes across postnatal development (Glra1, Grin2b, Kcnj3, and Kcnq3)." (PMID 36876911, 2023).
gastric cancer (1 paper, 2022). A primary or metastatic malignant neoplasm involving the stomach. "To find out the role of hub genes in the overall survival of gastric cancer we performed a multivariate Cox regression analysis, among 21 hub genes, the eight genes (KCNJ3, CPVL, ONECUT2, SLC19A3, DDC, PRSS21, F12, and GRTP1) were designated as independent indicators of poor prognosis." (PMID 35754804, 2022).
neuropathic pain (1 paper, 2024). Chronic pain caused by damage to nerve fibers. "Western blot analysis showed a significant decrease of KCNJ3 in the PM of DRG samples from neuropathic pain patients (P < 0.01, versus control)." (PMID 38530364, 2024).
cancer (12 papers, 2004 to 2025). A tumor composed of atypical neoplastic, often pleomorphic cells that invade other tissues. "The GIRK1 channel (encoded by the KCNJ3 gene) variants have been identified in both cancer cell lines and patients." (PMID 40236296, 2025). "Based on these facts we were interested to target the question whether somatic mutations of KCNJ3 have been already identified in malignant tumors and whether these mutations are functional and have effects on expression and function." (PMID 36483038, 2022). "It was previously reported that KCNJ3 overexpression contributed to cancer cells’ self-renewal and stemness." (PMID 36768373, 2023). "For example, with the increased KCNJ3 expression, cancer cells were sensitive to LOXO-101, NMS-E628, and sunitinib." (PMID 36686667, 2022). "MCF-7 cells stably overexpressing KCNJ3 (MCF-7GIRK1a;) formed significantly higher numbers of mammospheres compared to controls (p < 0.01), indicating that KCNJ3 upregulation might be involved in conferring self-renewal capacity to cancer cells and thus contributing to higher tumor aggressiveness." (PMID 27835900, 2016).
tumor (11 papers, 2004 to 2025). "Therefore, ER positive patients might be stratified into high risk and low risk groups based on the KCNJ3 levels in the tumor." (PMID 27835900, 2016). "We found that KCNJ3 expression in tumor cells significantly decreased after administering sunitinib through drug sensitivity analysis." (PMID 36686667, 2022). "Taken together, we propose a role of KCNJ3 in conferring tumor aggressiveness via invasion, metastasis and increased self-renewal capacity." (PMID 27835900, 2016). "Analysis of TCGA gene expression data of 105 tumor samples with corresponding normal breast samples showed significantly higher KCNJ3 mRNA levels in the tumors when compared to normal breast tissue (median 14.6 vs. 6.6 normalized counts; p < 0.001)." (PMID 27835900, 2016). "Therefore we favor the hypothesis that the tumor promoting effect of KCNJ3 overexpression is provoked by the corresponding protein(s)." (PMID 27519272, 2016). "The results proved that KCNJ3 expression is present in tumor cells, but not in non-neoplastic cells including normal mammary ducts." (PMID 27835900, 2016). "Here, we used a highly sensitive and specific RNA in situ hybridization technique for the validation of our findings, that showed positive signals in tumor cells but not in peritumoral tissue, and that allowed to clearly discriminate between patients with low and high KCNJ3 expression." (PMID 27835900, 2016).
KCNJ3 also shares sentences with these, for which no sentence is quoted: epilepsy (6 papers); amyloidosis (2); Anxiety (2); hypertrophic cardiomyopathy (2); lung carcinoma (2); small cell lung carcinoma (2); adenocarcinoma (1); bipolar depression (1); Blindness (1); brain diseases (1); carcinoid (1); cardiovascular disease (1); channelopathy (1); depression (1); familial atrial fibrillation (1); fragile X syndrome (1); glioma (1); heart failure (1); Hypoinsulinemia (1); idiopathic generalized epilepsy (1); Insulin resistance (1); intellectual disabilities (1); lung adenocarcinoma (1); medulloblastoma (1); myopathy (1); neurodegenerative disease (1); pancreatic cancer (1); Parkinsonism (1); Sinus bradycardia (1); squamous cell carcinoma (1).
A further 3 diseases each share a sentence with KCNJ3 in 1 paper.